KIT (KIT proto-oncogene, receptor tyrosine kinase)
Diseases named in the same sentence as KIT in open-access papers (continued):
Sharing a sentence is not in itself a finding about the gene and the disease.
melanoma (continued). "Despite the fact that c-KIT mutation occurred at a lower incidence than BRAF and NRAS genes in most of the melanoma patients, it represented 36% of acral lentiginous melanomas in cutaneous melanoma." (PMID 35720122, 2022). "The value of ORR was similar in nilotinib‐treated/KIT‐altered melanoma but was much lower in dasatinib‐treated individuals." (PMID 36254250, 2022). "Other melanoma mutations associated with the MAPK pathway take place within NRAS and KIT genes and account for 15–30% and 1–2% of cutaneous melanoma genetic alterations, respectively." (PMID 35158770, 2022). "Based on the part of VEGF and KIT in melanoma, they conducted a phase II trial of Sunitinib for patients with acral and mucosal melanomas." (PMID 36588679, 2022). "Several other c-KIT inhibitors such as dasatinib, sunitinib, sorafenib, and masitinib have been studied as future therapeutic agents for melanoma; however, further studies are needed to evaluate their clinical efficacy." (PMID 35954441, 2022). "Although mutations in SPRED1 and KIT are relatively weaker activators of the RAS pathway compared to the BRAFV600E or NRASQ61R mutants, they frequently occur together to drive mucosal melanoma." (PMID 35234863, 2022). "While BRAF-V600E is the most common pathogenic mutation seen in cutaneous sun-exposed melanomas, mucosal and anogenital melanomas usually lack BRAF mutations and instead harbor KIT alterations." (PMID 36407184, 2022). "Preclinical studies revealed a potent antitumor activity of an anti-c-KIT DM1-conjugated ADC on several c-KIT-positive solid cancers including melanoma and leukemia." (PMID 35159045, 2022). "Inhibitors of c-KIT, including Nilotinib, Dasatinib and Imatinib, have all been assessed in clinical trials and have delivered disappointing results with minimal activity in c-KIT-mutant melanoma patients." (PMID 36232957, 2022). "While clinical trials support the potential benefit of combination therapy in the treatment of melanoma, more clinical trials are necessary to fully understand the role of KIT inhibitors in combination with immunotherapy." (PMID 35954441, 2022). "The average level of KIT in melanoma was 65-fold higher than that in adjacent normal tissues, whereas PTEN, cAMP, and BCL2 were downregulated almost twofold." (PMID 35893303, 2022). "Several genes have been identified as genetically altered drivers of melanoma tumorigenesis, such as NRAS, CDNK2A, MITF, PTEN, KIT, GNAQ, GNA11 or CTNNB1, but most (60%) melanomas have BRAF gene mutations." (PMID 35326682, 2022). "Immunotherapy in combination with c-KIT inhibitors provides hope for future therapeutic responses in mutant melanoma." (PMID 36232957, 2022). "It is well known that the VEGF and KIT are potential targets for alternative therapeutics in malignant melanoma, and they are recognized to play a pivotal role in the pathogenesis and metastasis of melanoma." (PMID 36588679, 2022). "Ponatinib had a stronger affinity for KIT and was a more potent inhibitor when compared to imatinib, suggesting the need for future studies with newer TKIs in KIT mutant melanomas." (PMID 34831002, 2021). "Those are more common in the mucous and acral subtypes and KIT is regarded as major oncogene in Asian melanomas, where the prevalence of these subtypes is high." (PMID 34889232, 2021). "One melanoma carried a NRAS mutation (p.Q61R), and another melanoma carried a KIT mutation (exon 11)." (PMID 34065883, 2021).
melanoma (continued). "In a series of 444 mucosal melanomas from a European population investigated by Sanger sequencing, NRAS, KIT and BRAF mutations were evenly distributed across the different mucosal melanoma subgroups." (PMID 34571863, 2021). "No clinical trials have been reported to date with single-agent MEK or KIT inhibitors in melanoma patients with brain metastases." (PMID 34859235, 2021). "Other studies using NGS and cancer hotspot panels in paired melanoma samples found the same main driver mutations (BRAF, NRAS, KIT)." (PMID 34680222, 2021). "Increased signaling activity of the mitogen‐activated protein kinase (MAPK) pathway is a hallmark of melanoma and can be attributed to mutations in the BRAF, NRAS, KIT, or NF1 genes." (PMID 32767816, 2021). "Activating mutations in c-KIT are identified in approximately 15.6% of mucosal melanomas and 23% of acral melanomas and these numbers rises up to 39% and 36% respectively when KIT copy number increases." (PMID 33807778, 2021). "Here, we report a canine case of malignant melanoma that transiently responded to toceranib treatment and present details on the molecular analysis of the KIT that was expressed in the tumor of this case." (PMID 33827546, 2021). "The most frequent mutations seen in mucosal melanomas were in SF3B1 (27%), KIT (18%), and NF1 (17%)." (PMID 33724703, 2021). "This trial has paved the way for further investigation into the role of TKIs in KIT mutant melanomas." (PMID 34831002, 2021). "Amongst the mucosal melanoma, 34 underwent mutational testing and 4 patients had BRAF mutations (3 had v600 codon mutation and 1 non-v600 codon mutation) and another 4 had KIT mutations." (PMID 35211204, 2021). "KIT expression utility is enhanced by its discrepancy between benign nevi with dermal component and invasive superficial spreading melanoma." (PMID 34769348, 2021). "Survival analysis showed that the OS rate of patients with melanoma in the high expression group of KIT and VWF was significantly reduced." (PMID 34582363, 2021). "The overall frequency of main mutations in mucosal melanomas is as follows: NRAS (8%), BRAF (6%), neurofibromin 1 (NF1) (14%), KIT (13%), splicing factor 3b subunit 1(SF3B1) (15%)." (PMID 35008570, 2021). "The first results showed clinical benefit of nilotinib in some patients with melanoma harboring KIT alterations previously treated with KIT inhibitor (imatinib) but its efficacy in brain metastases was limited and needs further investigation." (PMID 33918490, 2021). "A gene signature of KIT/CD117–expressing CD33+ subset correlates with decreased overall survival in TCGA melanoma samples and represents a novel candidate biomarker." (PMID 33857287, 2021). "c-KIT has been shown to drive melanocyte proliferation and melanoma survival through activation of the phosphatidylinositol 3-kinase (PI3K) and mitogen-activated protein kinase (MAPK) pathways." (PMID 33807778, 2021). "In a recent trial of 78 melanoma patients harboring KIT alterations, the median overall survival for imatinib is 13.1 months and the objective response rate is 21.8%." (PMID 34350118, 2021). "This is an open-label, single-arm, phase I/II clinical trial involving Japanese patients with metastatic KIT-mutant melanoma that are refractory to standard therapy including anti-PD-1 therapy." (PMID 34889232, 2021). "Particularly, in 2015, a phase II trial with nilotinib in c-KIT melanoma was launched for patients who experienced disease progression, innate resistance to a prior KIT inhibitor, and a cohort of patients with brain metastases." (PMID 33918490, 2021). "One study obtained patient-derived tumor xenograft cells from KIT mutant melanomas and tested the efficacy of KIT inhibitors in vitro and in vivo." (PMID 34831002, 2021).
melanoma (continued). "The most important signaling pathways in c-KIT-derived melanomas are the PI3K/AKT and the MAPK pathways." (PMID 34831002, 2021). "Single-cell RNA-seq analysis identified a gene signature of a KIT/CD117–expressing CD33+ subset that correlated with decreased overall survival in a TCGA melanoma cohort." (PMID 33857287, 2021). "Up to date, several clinical trials have been conducted to target KIT gene alterations in melanoma with unsatisfied efficacies." (PMID 34889232, 2021). "It is an FDA-approved drug for chronic myeloid leukemia (CML) that showed promising outcomes in KIT-mutant PDX melanomas by comparing ponatinib to other RTK inhibitors." (PMID 33918490, 2021). "To uncover potential tumor-intrinsic mechanisms that regulate TLS formation, we have taken the novel perspective of evaluating TLS induction in melanomas impacted by common driver mutations in BRAF, PTEN, NRAS, KIT, PRDM1, and MITF." (PMID 33746966, 2021). "It was concluded that due to its efficacy and limited toxicity, imatinib remains the treatment of choice for patients with unresectable KIT+ melanoma." (PMID 33918490, 2021). "Evaluation of KIT expression in melanomas is also considered a possible screening method for tyrosine kinase inhibitor-targeted therapy efficacy." (PMID 34769348, 2021). "An open-labelled, single arm trial of combinational therapy with imatinib and pembrolizumab for unresectable or metastatic KIT-mutant melanoma, refractory to standard therapy, is currently recruiting." (PMID 33964953, 2021). "An approach conjugating imatinib to an antibody targeting c-KIT should be explored in melanoma cells, as this strategy has exhibited enhanced efficacy in several cancer types." (PMID 33807778, 2021). "Nevertheless, if the results of this study show promising efficacy and acceptable safety profile, it will contribute to the development of novel treatment option for patients with KIT-mutant melanoma that are refractory to standard therapy." (PMID 34889232, 2021). "The KIT gene plays an important role in melanocyte development and migration and its expression is elevated in advanced melanomas, but downregulated in the NTF2 high dox + cells." (PMID 34880267, 2021). "Concomitant KIT/SF3B1 mutations in sun-protected cases suggest a common tumorigenic process with genital and anorectal mucosal melanomas." (PMID 34359736, 2021). "Putative oncogenic activating mutations in BRAF (with a frequency of 40–60% in melanomas), NRAS, and KIT, as well as gene fusions, can signal through the MAPK and PI3K pathways, leading to uncontrolled cellular growth, proliferation, and survival." (PMID 34831002, 2021). "The role of KIT inhibition in patients with advanced melanomas and KIT alterations is rapidly expanding." (PMID 34831002, 2021). "Another recent study using the Cancer Genome Atlas (TCGA) and Gene Expression Omnibus (GEO) databases found that KIT expression is significantly lower in metastases as compared to primary melanomas." (PMID 35008286, 2021). "The c-KIT inhibitor imatinib is the most-studied adjuvant therapy and has so far shown only a suboptimal response in trials of mucosal melanomas." (PMID 33525348, 2021). "Following that, one phase 2 trial enrolled 21 patients with metastatic melanomas expressing at least one protein tyrosine-kinase (c-KIT, PDGFR, c-abl, or abl-related genes) to receive imatinib." (PMID 34831002, 2021). "Other KIT inhibitors such as dasatinib, sunitinib, and nilotininb have also exhibited responses in KIT-mutant melanomas." (PMID 34447613, 2021). "In this study, we analyzed the prognostic role of NRAS, KIT, BRAF, IGF2R and SF3B1 mutations in a series of mucosal melanomas." (PMID 34571863, 2021). "The ORR was 5% (a total of two PRs, one in a patient with a c-KIT exon 13 mutation, and one in a patient with a wild-type c-KIT), which emphasizes the concept of using these TKIs in c-KIT mutant melanomas only." (PMID 34831002, 2021).
melanoma (continued). "Stimulation of PI3K is required for full MAPK activity in response to c-KIT, suggesting that PI3K signaling is the dominant effector of c-KIT-mediated proliferation and survival in c-KIT-mutant melanomas." (PMID 33807778, 2021). "Current management of c-KIT mutant melanoma involves clinical trials using a c-KIT inhibitor or immunotherapy, as there is currently minimal data for the efficacy of immune-modulators in c-KIT mutant melanomas." (PMID 33807778, 2021). "Several trials have been conducted using KIT-targeted tyrosine kinase inhibitors in melanoma in both selected and unselected patient populations." (PMID 34447613, 2021). "Oncogenes linked to melanoma progression were also amplified, including NRAS, KIT and RAC1, the latter highly amplified in four patients in regions with LOH at copy numbers of 5 (patient ETH-F), 6 (patients CAS-E and SK-H) and 7 (patient CAS-F)." (PMID 33664264, 2021). "This is why we will discuss, within the present review, the effect of all c-KIT inhibitors tested in melanoma both in pre-clinical and clinical studies, with a specific focus on their efficacy according to the location of each exon mutation." (PMID 33918490, 2021). "Alternately, the CSD pathway through cumulative sun exposure leads to melanomas at usually exposed body sites with a substantial degree of solar elastosis that are characterized by a relatively increased proportion of NRAS and KIT mutations." (PMID 33648909, 2021). "Based on these promising evidences of ICI and KITi combination, we proposed to conduct the phase I/II clinical trial of imatinib mesylate (KITi) with pembrolizumab (anti-PD-1 antibody) for KIT-mutant melanoma patients who progressed after ICIs." (PMID 34889232, 2021). "NCT04598009 will evaluate binimetinib and imatinib in patients with stage III and IV KIT mutant melanomas." (PMID 34831002, 2021). "In mucosal melanomas, apart from driver mutations affecting the MAPK pathway (e.g., NRAS, BRAF, NF1, and KIT), mutations in CTNNB1 affecting Wnt/β-catenin pathway activation have also been reported." (PMID 34149718, 2021). "Our transcriptomics data showed that KIT gene expression is low in VGP primary melanoma and NTF2 high dox + cells but highly expressed in NTF2 low cells." (PMID 34880267, 2021). "Melanomas are most frequently characterized by BRAF and NRAS mutation and, more rarely, by c-KIT oncogene mutations, but tumor suppressor genes such as CDKN2A and PTEN have an important role in the development and prognosis of melanoma." (PMID 34209415, 2021). "Copy number variants, including loss of CDKN2A and gain of KIT, CDK4 and MYC, were frequently seen in mucosal melanomas." (PMID 34571863, 2021). "BRAF, MEK, NRAS, HRAS, KRAS, c-KIT, c-Met, VEGFR, PTEN, and PIK3CA mutations are common in melanoma." (PMID 34804979, 2021). "Inhibition of c-KIT-mutant melanoma with imatinib has produced objective response rate of 24.4% and disease control rate of 66.7% in patients with mutations in exons 11 (L576P) and 13 (K642E)." (PMID 33807778, 2021). "Sun-exposure-related melanoma has high melanocyte mutations such as NRAS, neurofibromin 1, KIT, and BRAFnonV600E compared with common mutation BRAFV600E in non-sun-exposed-related melanoma." (PMID 34199951, 2021). "If this study shows efficacy and acceptable safety profile, it will contribute to the development of novel treatment option for patients with KIT-mutant melanoma that are refractory to standard therapy." (PMID 34889232, 2021). "KIT is often overexpressed in melanoma, where it activates several signaling pathways and increases cell proliferation and metastasis." (PMID 34880267, 2021). "Although canine malignant melanoma cells often express KIT, six of the dogs with malignant melanoma that were previously treated with toceranib alone or in combination with other agents exhibited no objective response." (PMID 33827546, 2021).
melanoma (continued). "Although canine malignant melanoma cells often express KIT, a therapeutic effect for toceranib has yet to be reported for this tumor, with only a small number of patients studied to date." (PMID 33827546, 2021). "Currently, the use of TKI is reserved for the second or later line treatment in KIT mutant melanomas." (PMID 34831002, 2021). "Several large-scale sequencing studies in melanoma identified significantly mutated melanoma genes, such as NF), ARID2, TERT or RAC beside the well-established oncogenes including NRAS, BRAF or KIT." (PMID 33578810, 2021). "c-KIT-mutant melanoma is likely to develop resistance to molecular-targeted therapies due to pre-existing genetic alterations, reactivation of downstream c-KIT signaling pathways, and dynamic interactions with the microenvironment." (PMID 33807778, 2021). "KIT is often altered in mucosal malignant melanomas, where it activates intracellular signaling cascades, including the MAPK, PI3K, and JAK-STAT pathways." (PMID 32054078, 2020). "MNK1 activity is associated with invasion and metastasis in different types of melanoma, including KIT-mutant and BRAFv6000Emutant melanoma." (PMID 32340135, 2020). "The majority of melanoma cases demonstrate oncogenic activation of the KIT—NRAS—BRAF—MEK—ERK central axis that is a major regulator of cell differentiation and proliferation." (PMID 32085741, 2020). "The efficacy with KIT-directed therapies was modest, as further discussed in the mucosal melanoma section." (PMID 32825562, 2020). "The efficacy of kinase targeted therapy in patients with melanoma is influenced by B-Raf proto-oncogene, serine/threonine kinase (BRAF) and KIT proto-oncogene, receptor tyrosine kinase (KIT) mutations." (PMID 32260071, 2020). "Our group has shown that MNK1/2 inhibition using SEL201 blocks the progression of metastatic KIT melanoma, concomitant with suppression of eIF4E phosphorylation." (PMID 32517051, 2020). "It is of note that mutations in the nearest codons of such hot spots were also found to be clustered in KIT mutant melanomas." (PMID 31848942, 2020). "Growing evidence suggest that depending on the melanoma subtype, KIT can act as an oncogene or a tumor suppressor." (PMID 33256089, 2020). "Early ex vivo studies demonstrated that KIT inhibitors were efficient in killing KIT-mutant melanoma cell lines." (PMID 32344828, 2020). "We previously performed a pharmacodynamic study on 25 patients, using a quantitative PCR array, during a phase II clinical trial with nilotinib in KIT-altered melanoma." (PMID 32344828, 2020). "As recently reported, potential markers in melanoma are mutations (on BRAF, NRAS, KIT, GNA11/GNAQ, NF1, CDKN2AI, immunohistochemical biomarkers (such as PD-11 and PD-L1, as well as mutated BRAF and NY-ESO-1), miRNAs, and other serum molecules." (PMID 33302400, 2020). "KIT is a bona fide oncogene in a subset of melanoma and, ex vivo, KIT inhibitors are very efficient at killing KIT-mutant melanoma cell lines." (PMID 32344828, 2020). "KIT mutation is associated with older age, with CSD melanoma, the mucosal and acrolentiginous forms." (PMID 31848942, 2020). "Our research has shown that KIT-mutant melanoma patients have increased levels of MNK1 and phospho-eIF4E, and in breast cancer increased levels of p-MNK1 were associated with high-grade ductal carcinoma in situ." (PMID 32517051, 2020). "Treatment with KIT inhibitors resulted in a trend towards improved response in melanoma patients, with response rates of approximately 20%." (PMID 32344828, 2020). "Additional phase 2 trials using nilotinib in KIT-mutant melanoma patients (including MM) exhibited similar responses as seen with imatinib, demonstrating a clinical effect in patients with disease progression imatinib." (PMID 32825562, 2020).